TPSG1 (tryptase gamma 1)
Synonyms: PRSS31; TMT; trpA
Tractability: Small molecule: a high-quality ligand is known. Antibody: its Gene Ontology location is reachable by antibodies, with high confidence; UniProt predicts a signal peptide or a membrane-spanning region. PROTAC: a small molecule that binds it is known.
Target class: Serine protease; Enzyme; Serine protease PA clan; Serine protease S1A subfamily; Protease
Gene: Protein-coding gene on chromosome 16 (1,221,651 to 1,225,793, reverse strand). Ensembl gene ENSG00000116176.
Subcellular location: Membrane
Gene Ontology:
Molecular function: protein binding; serine-type endopeptidase activity; serine-type peptidase activity
Biological process: proteolysis
Cellular component: plasma membrane; membrane
Genetic constraint (gnomAD): Loss-of-function variants: 43 observed, 21.46 expected, observed/expected ratio (o/e) 2. The synonymous counts are far from expectation, so gnomAD's model fits this gene poorly and the ratio says little. Missense variants: 571 observed, 381.74 expected, observed/expected ratio (o/e) 1.5, 90% interval 1.4 to 1.6. Synonymous variants: 272 observed, 172.49 expected, observed/expected ratio (o/e) 1.58, 90% interval 1.43 to 1.74.
Homologues: Orthologues: chimpanzee TPSG1 (98% identical), macaque TPSG1 (92% identical), rat Tpsg1 (72% identical), mouse Tpsg1 (70% identical), zebrafish zgc:165423 (38% identical), zebrafish si:dkey-16l2.17 (36% identical), zebrafish zgc:92313 (35% identical), zebrafish prss60.2 (34% identical), zebrafish prss60.3 (34% identical), zebrafish prss60.1 (33% identical), zebrafish zgc:123295 (33% identical), zebrafish si:dkeyp-93a5.2 (32% identical), and 48 more. Paralogues in human: TPSAB1 (37% identical), TPSB2 (37% identical), TPSD1 (31% identical).
Diseases named in the same sentence as TPSG1 in open-access papers:
TPSG1 is named in the same sentence as 14 diseases in open-access papers, as found by Europe PMC text mining. Sharing a sentence is not in itself a finding about the gene and the disease. The quoted sentences say what the papers report.
COVID-19 (2 papers, 2021 to 2022). A disease caused by infection with severe acute respiratory syndrome coronavirus 2. "Quenching of proinflammatory pathways may be required for maintaining a high level of immune response as lower levels of TPSG1 indicate a lower risk of COVID-19 hospitalization." (PMID 36366544, 2022). "The C allele at rs13050728 associated with higher IFNAR2 expression in all tissues (except skeletal muscle), lower risk of COVID-19 hospitalization, and lower levels of plasma VEGFR2 and TPSG1." (PMID 33837377, 2021). "rs13050728 was associated with tryptase gamma 1 (TPSG1, P= 1.5×10-5) and vascular endothelial growth factor 2 (VEGFR2, P= 2.6×10-5), and both showed strong evidence of colocalization with COVID-19 hospitalization (PP.H4=0.96 for VEGFR2, PP.H4=0.96 for TPSG1)." (PMID 33837377, 2021).
itch (1 paper, 2022). "Pruritogens, including TAC1, IL-2, IL-31, TPSAB1, TPSB2, and TPSG1, and the key enzymes that are attributed to itch, including HDC and TPH1, were detected by RNA-seq." (PMID 35632808, 2022).
psoriasis (1 paper, 2021). An autoimmune condition characterized by red, well-delineated plaques with silvery scales that are usually on the extensor surfaces and scalp. "As a result, we found that the mRNA expression level of KIT, ENPP3, CMA1, CTSG, TPSAB1 and TPSG1 is decreased in PP compared with PN and NN, indicating the fraction of total mast cells is decreased in psoriasis." (PMID 34887864, 2021).
infection (5 papers, 2011 to 2024). The state of being infected such as from the introduction of a foreign agent such as serum, vaccine, antigenic substance or organism. "The levels of the Tpsg1 (tryptase gamma 1) transcript before infection and at day 3 p.i. were not significantly higher in C57Bl/6J (1.6 and 2.8 fold respectively) compared to DBA/2J mice, whereas at day 6 p.i., the levels were significantly higher in C57Bl/6J compared to DBA/2J mice." (PMID 21251300, 2011).
TPSG1 also shares sentences with these, for which no sentence is quoted: trachoma (5 papers); cancer (2); neurological diseases (2); asthma (1); chronic cystitis (1); colorectal cancer (1); emphysema (1); glioblastoma (1); melanoma (1); Sepsis (1).